IL1B (interleukin 1 beta)
Diseases named in the same sentence as IL1B in open-access papers (continued):
Sharing a sentence is not in itself a finding about the gene and the disease.
pulmonary hypertension (continued). "Alteration in chemerin signaling has already been linked to other pro-inflammatory conditions or cytokines (including TNF-α, IL-1β, and IL-6) upregulating CMKLR1 and CCRL2 which are also known to play crucial roles in pulmonary artery remodeling in pulmonary hypertension." (PMID 32848866, 2020). "The observed enhancement of EV-mediated HPASMCs:HPAECs communication with TGF-β1 and IL-1β, together with the results that showed increase in SMA, suggest that these EVs shall play a relevant role in the transition of HPAECs into mesenchymal cells during pulmonary hypertension development." (PMID 31703702, 2019). "IL-1β, TGF-β, and bradykinin, in human pulmonary artery smooth muscle, decreased the production of cAMP in response to subsequent administration of PGI2 analogues, providing data that inflammation can impair the actions of PGI2 analogues in pulmonary hypertension treatment." (PMID 22851816, 2012).
non-alcoholic fatty liver disease (37 papers, 2011 to 2026). "Other proinflammatory cytokines like tumor necrosis factor α (TNFα) and interleukin 1β (IL1β) increased as the nonalcoholic fatty liver disease progressed." (PMID 34597305, 2021). "Accordingly, an abundant expression of pro-inflammatory cytokines IL-1β and TNF-α is often associated with Non-Alcoholic Fatty Liver Disease (NAFLD)." (PMID 31935892, 2020). "Dysregulated BA profiles are linked to metabolic disorders including non-alcoholic fatty liver disease (NAFLD), diabetes, and atherosclerosis, with reciprocal crosstalk between inflammation and BA synthesis (e.g., IL-1β-mediated suppression of cholesterol 7α-hydroxylase (CYP7A1))." (PMID 41255527, 2025). "It has been reported that arsenic trioxide (As2O3) resulted in the nonalcoholic fatty liver disease/nonalcoholic steatohepatitis by inducing the classic pyroptosis pathway in HepG2 cells, accompanied by up-regulating the protein expressions of Caspase-1 and IL-1β." (PMID 34439523, 2021). "Other pathways include pathways in cancer (IL6 and AKT1), non-alcoholic fatty liver disease (AKT1 and IL1B), and the CAMP signaling pathway (AKT1)." (PMID 41601963, 2026). "Aucubin also prevented the elevation of MMP-9, MCP-1, apoC-III, ICAM-1, VCAM-1, TNF-α, IL-1β, and IL-6 levels after stimulation by apoC-III in 3T3-L1 cells and in mice with tyloxapol-induced nonalcoholic fatty liver disease (NAFLD)." (PMID 37241895, 2023). "Recently, it was discovered that when GPR35 was eliminated in the liver of non-alcoholic fatty liver disease (NAFLD) mice, there was an increase in inflammatory cytokines such as TNFα, IL6, and IL1β in the liver." (PMID 38035084, 2023). "Additionally, verapamil can treat non‐alcoholic fatty liver disease by inhibiting the TXNIP/NLRP3 pathway and reducing the level of IL‐1β and IL‐18 to attenuate hepatic metaflammation." (PMID 34031983, 2021).
non-alcoholic steatohepatitis (37 papers, 2012 to 2025). "Tim-3 deficiency in nonalcoholic steatohepatitis mice contributed to enhanced production of ROS, IL-1β, and IL-18." (PMID 37393392, 2023). "Inflammatory mediators tumor necrosis factor (TNF) and interleukin 1 beta (IL1β), primarily derived from hepatic macrophages in the liver, play a crucial role in the progression of nonalcoholic steatohepatitis (NASH)." (PMID 39778469, 2025). "Chen and colleagues established the formation and activation of the NLRP3 inflammasome and IL-1β in nonalcoholic steatohepatitis." (PMID 37568105, 2023). "Interleukin-1β (IL-1β) is a key mediator of non-alcoholic steatohepatitis (NASH), a chronic liver disease, and of systemic inflammation-driven aging." (PMID 36611037, 2023). "The expression levels of pro-inflammatory cytokines, including tumor necrosis factor-α (TNF-α), IL-6, and IL-1β, were significantly decreased in the non-alcoholic steatohepatitis by inhibiting ferroptosis." (PMID 37970439, 2023). "IL-1β is produced from HSCs stimulated by lipopolysaccharide (LPS) or palmitic acid which are likely activators of PKR in non-alcoholic steatohepatitis (NASH)." (PMID 30794626, 2019). "In addition, MCs can also induce NLRP3-mediated inflammatory responses in liver cells, which will increase the expression of IL-1β in cells and promote the progression of non-alcoholic steatohepatitis." (PMID 37104231, 2023). "Using flow cytometry, we evaluated the plasma levels of IL-1β, IL-6, IL-12, TNF and IL-10 and their association with clinical and biochemical parameters of liver function during simple steatosis (NAFL) and nonalcoholic steatohepatitis (NASH) in biopsy-proven patients." (PMID 34447378, 2021). "Previous studies have shown that CPT can reduce the activation of caspase-1 activity and the secretion of IL-1β in mouse models of NLRP3 inflammasome-mediated diseases such as endotoxemia syndrome and nonalcoholic steatohepatitis (NASH)." (PMID 41154678, 2025). "Our research group has previously demonstrated that DM509 treatment to non-alcoholic steatohepatitis mice decreased liver CXCR3, CXCL9, CXCL10, TNFα, IL-1β, and TGF-β expression." (PMID 38235144, 2023). "Together they promote the development of non‐alcoholic steatohepatitis (NASH) characterized by liver inflammation and activated inflammatory cytokine signaling pathways stimulated by TNF‐α, IL‐1β, KC/CXCL1, MCP1/CCL2, and others." (PMID 35830259, 2022). "SLBZS treatment inhibited the TLR4/p38 MAPK signaling pathway, attenuating lipid metabolic disturbance, reducing IL-1β, TNF-α, and IL-6 levels, and reversing non-alcoholic steatohepatitis progression." (PMID 32460745, 2020). "With regard to the cytokines, we focused on measuring IL-1β, IL-6, and TNF-α because these have been deemed the most relevant overall to the pathogenesis of alcoholic and non-alcoholic steatohepatitis." (PMID 26339530, 2012). "IL-1β, IL-6, and TNF-α were measured because these cytokines have demonstrated roles as mediators of injury in both alcoholic and nonalcoholic steatohepatitis, and PPAR agonists function in part by regulating proinflammatory responses." (PMID 26339530, 2012). "Similarly, in non-alcoholic steatohepatitis (NASH), Kupffer cell activation via TLR4 and NLRP3 inflammasomes promotes release of cytokines such as IL-1β and IL-18." (PMID 41585231, 2025). "In a study in a non-alcoholic steatohepatitis mouse model, the hot water extract of C. longa inhibited the hepatic production of TNF-α, IL-1β, and IL-6, and in our earlier clinical studies, C. longa extract improved systemic inflammatory markers, including hsCRP, TNF-α, and IL-6." (PMID 36145139, 2022). "Among them, S1PR1 controls the expression of IL-1β in response to Newcastle disease virus by modulating the NLRP3/caspase-1 inflammasome pathway and enhances inflammation and fibrosis in the kidney, while S1PR4 promotes nonalcoholic steatohepatitis by activating NLRP3 inflammasomes." (PMID 38003456, 2023).
non-alcoholic steatohepatitis (continued). "Moreover, it has been reported that hepatic ferroptosis plays an important role as the trigger for initiating inflammation in non-alcoholic steatohepatitis, showing that the expressions of TNF-α, IL-6, and IL-1β were significantly upregulated following ferroptosis." (PMID 37425328, 2023). "While we did not observe increased inflammation in the liver on a high-fat diet based on p65 phosphorylation, TNF-α expression, or IL-1β expression, this is likely because 8 weeks on a HFD primarily leads to an NAFLD phenotype rather than progression to non-alcoholic steatohepatitis." (PMID 37432201, 2023).
osteosarcoma (37 papers, 2013 to 2025). A usually aggressive malignant bone-forming mesenchymal neoplasm, predominantly affecting adolescents and young adults. "IL-1β is, in part, secreted by tumor-associated macrophages in osteosarcoma, where it has been proposed to promote metastasis, an effect which was reversed by anakinra treatment." (PMID 41008853, 2025). "A particular cytokine, IL-1β, was associated with metastatic presentation and inferior event-free survival in patients with osteosarcoma." (PMID 41008853, 2025). "Perhaps most significantly, elevated IL-1β at diagnosis was associated with metastatic presentation and inferior event-free survival in patients with osteosarcoma." (PMID 41008853, 2025). "M2-like TAMs induced resistance to chemotherapy in primary osteosarcoma cells, by releasing IL-1β, which in response caused the overexpression of IL-34, vasculogenesis, and osteosarcoma growth." (PMID 37958467, 2023). "Plasma levels of IL-1β were higher in patients with sarcoma than in healthy controls, and patients with osteosarcoma in particular with elevated IL-1β levels at diagnosis were more likely to present with metastatic disease and had a shortened EFS." (PMID 41008853, 2025). "Osteosarcoma had 25 significant relationships, notably including IL-4/IL-1β (r2 = 0.58, p = 0.000048), IL-12 p40/IL-4 (r2 = 0.47, p = 0.0015), CXCL5/IL-27 (r2 = −0.48, p = 0.001), CXCL14/IL-15 (r2 = 0.66, p = 0.0000021)." (PMID 41008853, 2025). "Other genes, including WNT5A (AUC = 0.935), GCA (AUC = 0.922), ANXA6 (AUC = 0.909), ARPC3 (AUC = 0.909), and IL1β (AUC = 0.766) also exhibited heterogeneous levels of predictive precision for detecting osteosarcoma." (PMID 40616392, 2025). "Through screening, Mifepristone, which can act on BIRC5 and IL1β at the same time, has a very effective osteosarcoma treatment effect." (PMID 40616392, 2025). "Our research found that compared to normal tissues, the expression level of MIRC5 was increased in osteosarcoma tissues, while the expression of IL‐1β was decreased." (PMID 40616392, 2025). "IL1β treatment has been shown to reduce the sensitivity of osteosarcoma cells to chemotherapeutic agents in animal studies." (PMID 39359731, 2024). "A Kaplan–Meier survival curve was used to study the relationship between ZFP36L2 and IL1β in osteosarcoma." (PMID 39767767, 2024). "Cell–cell communication analysis indicates that ZFP36L2 targets TNF in IL1β+ osteosarcoma, thereby improving prognosis." (PMID 39767767, 2024). "IL-1β release can lead to the transcription of signaling pathways previously found to promote chemoresistance in osteosarcoma and initiate a pro-tumoral response contributing to metastasis." (PMID 39359731, 2024). "The amount of type II collagen protein was reversed in IL-1β-induced osteosarcoma cells, while MMP-13 and other metal matrix proteases were expressed in cartilage tissues." (PMID 36982198, 2023). "On the other hand, irisin reversed the IL-1β-induced IkBa expression and p65 phosphorylation levels in osteosarcoma cells, as shown by lower TNF-α expression in chondrocytes cultivated in vitro." (PMID 36982198, 2023). "the levels of IL‐1β were elevated within three days after surgery in patients with osteosarcoma who underwent surgical treatment, as well as in traumatized mice." (PMID 37585564, 2023). "The expression of MMP-13 and other metal matrix proteases in cartilage tissues was down-regulated, and the protein level of type II collagen in IL-1β-induced osteosarcoma cells was reversed." (PMID 36062149, 2022). "Based on in vitro and in vivo findings, it was reported that expression of caspase-1 and its downstream target Interleukin-1β (IL-1β) was higher in osteosarcoma cells as compared to normal cells." (PMID 36144625, 2022). "Here, we demonstrate that chemotherapeutic agents such as doxorubicin induce EV release, stimulating neighboring cancer cells to express IL-6 and IL-1β in osteosarcoma." (PMID 35326493, 2022).
osteosarcoma (continued). "On the other hand, irisin reduced TNF-α expression in chondrocytes cultured in vitro demonstrated that irisin reversed IL-1β-induced IkBa expression and p65 phosphorylation levels in osteosarcoma cells." (PMID 36062149, 2022). "TGF-β2 enhances versican expression in fibrosarcoma and osteosarcoma cells and IL-1β increases versican levels in lung fibroblasts." (PMID 28035060, 2017). "Here, we investigate the effect of 2-hour IL-1β stimulation on the differentiation and paracrine activity of hMSCs in coculture with osteosarcoma cells in vitro." (PMID 26798640, 2015). "Here, we investigated the direct and indirect long-term effects of 2-hour short-term IL-1β stimulation of human MSCs cocultured with the osteosarcoma cell line MG63-GFP in a transwell system that allowed indirect cell communication." (PMID 26798640, 2015). "In addition, patients with osteosarcoma who had high IL-1β levels had worse EFS than those with low IL-1β (p = 0.0097)." (PMID 41008853, 2025). "Most significantly, we found that patients with osteosarcoma who have high levels of plasma IL-1β at diagnosis are more likely to have metastatic disease at presentation and have a shorter event-free survival (EFS) than those with lower levels of this cytokine." (PMID 41008853, 2025). "Bioinformatics analysis identified six exosome‐associated osteosarcoma genes (WNT5A, GCA, ANXA6, BIRC5, IL1β, and ARPC3) that could serve as potential biomarkers." (PMID 40616392, 2025). "Although 23.1% of patients with Ewing sarcoma who had low IL-1β had metastatic disease compared with 42.9% with high IL-1β (p = NS), in the osteosarcoma cohort, only 4% of patients with low IL-1β had metastatic disease compared to 37.5% in the high IL-1β group (p = 0.036)." (PMID 41008853, 2025). "The survival analysis results show that ZFP36L2 can serve as a biomarker in IL1β+ osteosarcoma." (PMID 39767767, 2024). "IL-1β secreted by M2-TAMs supports osteosarcoma metastasis via the RASSF1A-Wnt pathway." (PMID 39359731, 2024). "In addition, the expression of IL-17A, IL-1β and IL-10 was proven to be involved in osteosarcoma carcinogenesis." (PMID 39252946, 2024). "Additionally, Infliximab has also been shown to inhibit IL-1β and IL-6 gene expression in the human osteosarcoma cell line MG-63." (PMID 39596421, 2024). "Our data indicated that doxorubicin enhanced IL-1β and IL-6 levels in osteosarcoma." (PMID 35326493, 2022). "Next, we confirmed whether the induction of IL-1β in conditioned medium derived from doxorubicin affected the PD-L1 levels in osteosarcoma." (PMID 35326493, 2022). "In patients with osteosarcoma, IL16 variants were related to higher levels of IL-16 and, consequently, in the effects in the production of other tumor-related inflammatory cytokines, such as TNF-α and IL-1β." (PMID 32915917, 2020). "In another study, both IL-1β and TNFα promoted MG-63 osteosarcoma cell adhesion on laminin." (PMID 27556857, 2016). "Therefore, we infer that it may inhibit MIRC5 and promote the expression of IL‐1β to achieve the inhibitory effect on osteosarcoma." (PMID 40616392, 2025). "IL-1β in particular may be a valuable therapeutic target for osteosarcoma patients." (PMID 41008853, 2025). "Taken together, IL-1β may inhibit osteosarcoma migration through enhancement of ACE2 levels." (PMID 37608279, 2023). "Furthermore, a reduced expression of caspase-1 and IL-1β via the administration of berberine could significantly suppress the cell viability in osteosarcoma." (PMID 34393801, 2021). "Moreover, after treatment with chemotherapy medications, macrophages secreted IL-1β, which could activate downstream cancer signaling pathways and reduce the sensitivity of osteosarcoma to chemotherapeutic drugs." (PMID 33363016, 2020). "We found that IL1B was highly expressed in MDSC, and its receptor IL1R1 was highly expressed in osteosarcoma cells, along with downstream upregulation of target pathways." (PMID 40647416, 2025).
osteosarcoma (continued). "The expression profiles of six core genes (WNT5A, GCA, ANXA6, BIRC5, IL1β, and ARPC3) were contrasted between the control and osteosarcoma groups." (PMID 40616392, 2025). "For example, IL1B was highly expressed in MDSC, and its receptor IL1R1 was highly expressed in osteosarcoma cells." (PMID 40647416, 2025). "TAM-derived molecules, such as IL-1β and C-C motif chemokine ligand 18 (CCL18), significantly promote osteosarcoma metastasis." (PMID 39359731, 2024). "The NIPP-induced upregulation of IL1B as observed in the present study was also found in PDL and osteosarcoma cells." (PMID 36078148, 2022). "The present results of the western blot revealed that the NLRP3 as well as caspase-1, GSDMD, IL-1β, and IL-18 proteins decreased after NLRP3 blockage in osteosarcoma." (PMID 34393801, 2021). "Table I shows the quantitative densitometry results from the effects of inducers PMA, TNF-α, IL-1β and LPS on MMP-2 and -9 secretion by osteosarcoma and rhabdomyosarcoma cell lines." (PMID 24190483, 2014). "Similarly, miR-181b overexpression, as induced by IL-1β/NF-κB signalling, was shown to downregulate the expression of PTEN and thereby promote the proliferation of osteosarcoma cells." (PMID 39125612, 2024). "To determine whether doxorubicin enhanced TNF-α, IL-6, IL-1β, TGF-β, and IFN-γ expression in osteosarcoma, we treated MG63 and 143B cells as indicated." (PMID 35326493, 2022). "In response to doxorubicin, IL-1β, but not IL-6, allowed- osteosarcoma cells to promote the expression of PD-L1, and the elimination of IL-1β/IL-1 receptor signaling with IL-1 receptor antagonist reduced PD-L1 expression." (PMID 35326493, 2022). "Additionally, it showed an IL1B:IL1R interaction with TAMs and was related to increased chemoresistance in osteosarcoma." (PMID 35664733, 2022). "In addition, macrophages polarized in vitro with GM-CSF and further activated with MTP-PE and IFNγ are capable of inhibiting osteosarcoma growth by producing soluble factors, although independent of TNFα or IL-1β." (PMID 38919608, 2024).